ICAM1 (intercellular adhesion molecule 1)
Diseases named in the same sentence as ICAM1 in open-access papers (continued):
Sharing a sentence is not in itself a finding about the gene and the disease.
liver fibrosis (11 papers, 2009 to 2024). "Second, disruption of the Icam-1 gene that encodes ICAM-1 protein, a key adhesion molecule for neutrophil recruitment, also attenuated neutrophil infiltration and liver fibrosis in this model." (PMID 29552626, 2018). "Additionally, the blockade of Icam1 lowered the expression of fibrosis genes, decreased hepatic neutrophil infiltration, and mitigated liver fibrosis." (PMID 39040848, 2024). "In addition, Sirius Red and Masson Trichrome staining showed that Icam-1 KO mice had lower levels of liver fibrosis than WT mice, whereas body weight was comparable between these 2 groups." (PMID 29552626, 2018). "Suppression of inflammatory molecules, MIP-1α and ICAM-1 by LBE and RA indicates less activated hepatic stellate cells, following less α-SMA and COL1A1, the markers of liver fibrosis." (PMID 32331258, 2020). "To test whether neutrophils also contribute to the liver fibrosis in this model, we used 2 approaches to attenuate neutrophil infiltration via the inhibition of CXCL1 or ICAM-1, 2 important mediators for neutrophil infiltration." (PMID 29552626, 2018). "In mice identified molecules include liver fibrosis A-3/CD58, ICAM-1/CD54, and B7-2/CD86." (PMID 26339640, 2015). "KC have an essential role in liver fibrosis in mouse models of ASH and NASH, propagating hepatic inflammation via tumor necrosis factor (TNF) and leukocyte recruitment via intercellular adhesion molecule-1 (ICAM-1) and vascular cell adhesion molecule-1 (VCAM-1)." (PMID 30972062, 2019).
lung adenocarcinoma (11 papers, 2016 to 2025). A carcinoma that arises from the lung and is characterized by the presence of malignant glandular epithelial cells. "Notably, MARCHF9 has been implicated in the prognosis of lung adenocarcinoma, where it suppresses tumor progression by downregulating ICAM-1." (PMID 39185021, 2024). "We previously reported that cardamonin, a chalcone-type flavonoid, inhibited TNF-α-induced ICAM-1 expression in human lung adenocarcinoma A549 cells." (PMID 41302385, 2025). "In the present study, the effects of 13 oleanane-type triterpenoids on cell viability and NF-κB activation and the protein expression, intracellular trafficking, and N-glycosylation of ICAM-1 in human lung adenocarcinoma A549 cells were evaluated." (PMID 38892215, 2024). "The present results demonstrated that cucurbitacin B down-regulated TNF-α-induced ICAM-1 expression and the NF-κB signaling pathway in human lung adenocarcinoma A549 cells." (PMID 35806134, 2022). "In the present study, we found that cucurbitacin B decreased the expression of ICAM-1 in human lung adenocarcinoma A549 cells stimulated with TNF-α or interleukin-1α." (PMID 35806134, 2022). "In the course of our screening, quinacrine was initially found to inhibit the expression of intercellular adhesion molecule-1 (ICAM-1) in response to TNF-α in human lung adenocarcinoma A549 cells." (PMID 29207489, 2017). "Human lung adenocarcinoma A549 cells express cell-surface ICAM-1 when treated with inflammatory cytokines." (PMID 29207489, 2017). "We previously reported that ursolic acid, corosolic acid, and asiatic acid interfered with the intracellular trafficking and glycosylation of intercellular adhesion molecule-1 (ICAM-1) in human lung adenocarcinoma A549 cells stimulated with the pro-inflammatory cytokine interleukin-1α." (PMID 35630550, 2022). "In the present study, we found that cucurbitacin B reduced the level of ICAM-1 expression induced by TNF-α and IL-1α in human lung adenocarcinoma A549 cells." (PMID 35806134, 2022). "Subsequently, it is verified that 9 core targets for ginseng treatment of lung adenocarcinoma, namely, JUN, IL-1β, IL-2, ICAM1, HMOX1, MMP9, MMP2, PTGS2, and TNF, are closely related to the proliferation, migration, and apoptosis of lung adenocarcinoma cells." (PMID 32802118, 2020). "In the present study, we demonstrated that quinacrine decreased the expression of intercellular adhesion molecule-1 (ICAM-1) induced by tumor necrosis factor (TNF)-α and interleukin-1 (IL-1) α in human lung adenocarcinoma A549 cells." (PMID 29207489, 2017). "At the same time, in lung adenocarcinoma samples, LFA-1 expression was also clearly upregulated in metastatic regions, whereas ICAM-1 was detected primarily at the intersection between tumour cells and brain parenchyma." (PMID 27447568, 2016). "Meanwhile, according to the results of qRT-PCR, it is speculated that ginseng can treat lung adenocarcinoma by up-regulated JUN, IL-1β, IL-2, ICAM1, HMOX1, MMP9, and MMP2 targets and down-regulated PTGS2 and TNF genes." (PMID 32802118, 2020).
lupus nephritis (11 papers, 2011 to 2025). Glomerulonephritis in the context of systemic lupus erythematosus. "ICAM-1 is a representative adhesive molecule in neutrophil recruitment to the kidneys and is associated with lupus nephritis." (PMID 32655553, 2020). "In lupus nephritis patients, levels of urinary ICAM-1 were significantly higher in patients with advanced histological changes than in other groups." (PMID 30868076, 2019). "Moreover, several studies have shown that levels of soluble VCAM-1(sVCAM-1) and ICAM-1(sICAM-1) are also significantly increased in the serum and urine of patients with lupus nephritis and significantly correlate with disease activity indices." (PMID 25400916, 2013). "It was reported that ICAM-1 is highly expressed in endothelial cells of HBV-MN, IgA nephropathy and lupus nephritis." (PMID 35935760, 2022). "The importance of adhesion molecules in the pathogenesis of lupus nephritis was suggested by the observation that expression of vascular cell-adhesion molecule-1 (VCAM-1) and intercellular adhesion molecule-1 (ICAM-1) are elevated in affected kidneys." (PMID 25400916, 2013). "Although there is an association with the presence of renal involvement in SLE, a recent meta-analysis concluded that the current evidence does not support urinary ICAM-1 as an effective marker of lupus nephritis activity." (PMID 33604504, 2021). "Furthermore, JKAP-deficient T cells overproduced complement components, soluble ICAM-1, and soluble VCAM-1 in the kidney; these cytokines have been reported to be involved in lupus nephritis." (PMID 27557500, 2016).
osteoarthritis (11 papers, 2005 to 2025). A noninflammatory degenerative joint disease occurring chiefly in older persons, characterized by degeneration of the articular cartilage, hypertrophy of bone at the margins and changes in the synovial membrane. "Other reports also indicate that interleukin-1β up-regulates the expressions of intercellular adhesion molecule-1 and vascular cell adhesion molecule-1 in osteoarthritis fibroblast-like synoviocytes via nuclear factor -κB-mediated mechanism." (PMID 26771387, 2016). "Adhesion molecules ICAM-1 (CD54) and VCAM-1 (CD106) are expressed at higher levels in the synovial tissue of RA than in osteoarthritis and are implicated in the interaction between leukocytes and RA FLS that contributes to the synovitis." (PMID 16277688, 2005). "In pathological conditions, such as osteoarthritis and osteoporosis, ICAM-1 expression by osteoblasts may be increased by proinflammatory cytokines and contribute to bone resorption and loss of bone mass." (PMID 37888168, 2023). "E-selectin is highly expressed on endothelium in RA synovium, predominantly on venules and capillaries, whereas VCAM-1 and ICAM-1 are also expressed on other cell types, including ST macrophages, fibroblasts, and lymphocytes in RA synovium compared with osteoarthritis synovium." (PMID 22534470, 2012). "The effect of poor HKG selection was tested within donors and between sources for each MSC type on the expression amount of ICAM1 and IL8 by coding for players involved in MSC activity as therapeutics for osteoarthritis (OA)." (PMID 38338737, 2024). "Osteoarthritis research society international (OARSI) score in cartilage was markedly increased, along with increased MMP‐3, MMP‐13, ADAMTS‐5, ICAM‐1, ERK and p‐ERK expression." (PMID 33939302, 2021).
peritonitis (11 papers, 2004 to 2025). Inflammation of the peritoneum (tissue that lines the abdominal wall and covers most of the organs in the abdomen). "Peritonitis was induced in both male wild-type and P-selectin/ICAM-1 double deficient (P/I null) mice by cecal ligation-puncture (CLP)." (PMID 15274743, 2004). "Four rats with peritonitis and three healthy control rats were infused with anti-ICAM-1 antibody-coated MBs radiolabeled with gamma-emitting 99mTc for SPECT imaging." (PMID 31719897, 2019). "SPECT imaging showed an approximate doubling of signal intensity from the abdomen of rats with peritonitis, compared with healthy controls, after injection of anti-ICAM-1-MBs." (PMID 31719897, 2019). "Macrophages isolated from rats with peritonitis showed a 23% increase in the MFI of the Cy3 signal for anti-ICAM-1-MB compared with macrophages from healthy rats, and a 46% increase compared with control MBs (MB-streptavidin)." (PMID 31719897, 2019). "As for acute inflammation, we found that neovestitol reduced neutrophil migration, leukocyte rolling and adhesion, as well as expression of ICAM-1 in the mesenteric microcirculation during lipopolysaccharide-induced acute peritonitis." (PMID 27819273, 2016). "Monitoring of TNF-α-induced expression of the adhesion molecules VCAM-1, ICAM-1 and E-selectin by flow cytometry was used to confirm NF-κB inhibition in endothelial cells, and thioglycollate-induced peritonitis in mice to confirm effects in vivo." (PMID 24329519, 2014). "In the present study, P-selectin/ICAM-1 appears to be partially involved in neutrophil migration into the peritoneal cavity but only during the early stages of the response to CLP-induced peritonitis." (PMID 15274743, 2004). "Both neovestitol and vestitol were reported to modulate the NF-κB pathway in lipopolysaccharide (LPS)-activated macrophages and decreased neutrophil migration, rolling and adhesion, by reducing the expression of ICAM-1 in an in vivo LPS-induced acute peritonitis model." (PMID 32707856, 2020). "Plumericin inhibited NF-κB-mediated transactivation of a luciferase reporter gene (IC50 1 μM), abolished TNF-α-induced expression of the adhesion molecules VCAM-1, ICAM-1 and E-selectin in endothelial cells and suppressed thioglycollate-induced peritonitis in mice." (PMID 24329519, 2014). "The coexpressed CD11b and ICAM-1 of cells in PVs in peritonitis and control rats indicated that the PVs may be involved in inflammation." (PMID 24069050, 2013). "There are some evidences that NO inhibits neutrophil migration by a mechanism dependent on the expression of ICAM-1 on mesenteric microcirculation vessels of mice subjected to experimental acute peritonitis by an injection of either LPS, carrageenan (Cg), or (fMLP)." (PMID 21253492, 2010). "Therefore, this study was undertaken to examine the role of P-selectin and ICAM-1 molecules in the wild-type and P/I null mice subjected to a short and longer periods of peritonitis induce by CLP." (PMID 15274743, 2004). "Therefore, the objective of this study was to determine the role of P-selectin and ICAM-1 in neutrophil infiltration into the peritoneal cavity during early and late phases of peritonitis." (PMID 15274743, 2004). "Therefore, the goal of the study presented here was to investigate the role of ICAM-1 and P-selectin in peritonitis induced by CLP under a short and longer period of injury." (PMID 15274743, 2004). "Successful targeting of ICAM-1, VCAM- 1, and e-selectin using layer-by-layer MBs has been shown in human and murine endothelial cells and in a zymosan induced peritonitis model." (PMID 36327225, 2022). "Although the study presented in this article suggests a non-role of ICAM-1 in neutrophil infiltration into the peritoneal cavity in response to peritonitis, it has to be noted that the P/I null mice are not a true ICAM-1 knockout." (PMID 15274743, 2004).
peritonitis (continued). "The data presented in this study have shown a clear, time-dependent neutrophil migration and infiltration into peritoneal cavity in responses to peritonitis, which is independent of P-selectin and ICAM-1 adhesion molecules." (PMID 15274743, 2004). "The data suggest that alternative adhesion pathway(s) independent of P-selectin and ICAM-1 can participate in neutrophil migration during peritonitis and that the mode of stimuli and duration of the injury modulate the neutrophil infiltration." (PMID 15274743, 2004). "To examine whether the antibody-labeled MBs could target macrophages, we isolated peritoneal macrophages from a rat model of peritonitis and healthy control rats to compare the uptake of anti-ICAM-1-MBs in inflamed and non-inflamed cells." (PMID 31719897, 2019). "Therefore, it is likely that the increased abdominal signal in animals with peritonitis as quantified by SPECT imaging was not only because of abundance of inflammatory macrophages, but also because of increased expression and recognition of ICAM-1 by MBs." (PMID 31719897, 2019). "In this study, the authors treated the experimental peritonitis in mice with chemical inhibitors for NO synthase (NOS) and demonstrated an increase in the migration of neutrophils into venular endothelium and enhanced the expression of ICAM-1 on the endothelium." (PMID 21253492, 2010). "Moreover, whether acute peritonitis correlated with the occurrence of celiac PVs was investigated by fluorescent staining with 4′,6-diamidino-2-phenylindole (DAPI) and Alexa Fluor 488 phalloidin, as well as immunofluorescent staining with CD11b and intercellular adhesion molecule-1(ICAM-1)." (PMID 24069050, 2013).
pulmonary hypertension (11 papers, 2016 to 2025). Increased pressure within the pulmonary circulation due to lung or heart disorder. "Fluoxetine, administered for 3 weeks to rats with induced pulmonary arterial hypertension, decreased ICAM-1 protein expression in lung tissues." (PMID 33945102, 2021). "It reduced the expression level of IL-6, TNF-α, and intercellular adhesion molecule-1 (ICAM-1) by regulating NF-kB signaling in pulmonary artery hypertension rat." (PMID 31024252, 2019). "Bosentan treatment has been shown to significantly reduce (ICAM‐1), IL‐6 and brain natriuretic peptide (BNP) in patients with pulmonary arterial hypertension." (PMID 40034063, 2025). "In keeping with this, increased IL32 staining was observed in tissue sections from patients with pulmonary hypertension, whereas in cellular models, IL32 silencing decreased endothelial cells proliferation and the expression of the adhesion molecule ICAM-1." (PMID 37108628, 2023).
arteriosclerosis (10 papers, 2017 to 2025). A vascular disorder characterized by thickening and hardening of the walls of the arteries. "It was also reported that GLP-1 receptor stimulation increased the expression of eNOS and suppressed the intercellular adhesion molecule-1 (Icam-1) expression of aortic endothelial cells in arteriosclerosis model mice." (PMID 33446799, 2021). "However, one study observed higher ICAM-1 levels in patients with arteriosclerosis." (PMID 39091977, 2024). "Intercellular adhesion molecule 1 (ICAM-1), a crucial factor in upregulating endothelial inflammation and vascular sclerosis, has been reported to be regulated by NSUN2-mediated m5C mRNA methylation." (PMID 41583468, 2025). "The vascular endothelium is thus a crucial site in the pathogenesis of arteriosclerosis, where the interaction between monocytes and endothelial cells is mediated by CAMs like VCAM-1 and ICAM-1." (PMID 39534464, 2024). "Numerous domestic and international studies have demonstrated that in arteriosclerosis, increased expression of VCAM-1 and ICAM-1 leads to intercellular adhesion, exacerbating vascular stenosis and thrombus formation." (PMID 39534464, 2024). "The expression of intercellular adhesion molecule-1 (ICAM-1), vascular cell adhesion protein 1 (VCAM-1), and E-selectin increases in VECs during the initiation and progression of arteriosclerosis." (PMID 35053238, 2022). "Moreover, the aqueous extract of Wu-Ling-Zhi could down-regulate the expression of intercellular adhesion molecule-1 in experimental atherosclerotic rats and reduce the degree of vascular endothelial lesions, which may account for the anti-arteriosclerosis inflammatory effects of Wu-Ling-Zhi." (PMID 31528199, 2019).
liver steatosis (10 papers, 2010 to 2026). "After further adjustment including VAT, ICAM-1 (OR = 2.67, P = .02), adiponectin (OR = 0.57, P = .003), and osteoprotegerin (OR = 0.48, P = .03) remained significantly associated with fatty liver." (PMID 28929125, 2017). "Among HIV-infected men, higher ICAM-1 and lower osteoprotegerin levels were independently associated with fatty liver." (PMID 28929125, 2017). "Among HIV-infected men, ICAM-1 was the only proinflammatory marker associated with greater odds of fatty liver (OR = 2.67, P = .02), whereas higher adiponectin (OR = 0.57, P = .003), and osteoprotegerin levels (OR = 0.48, P = .03) were associated with lower odds." (PMID 28929125, 2017). "The biomarkers that we found to be independently associated with fatty liver, lower adiponectin, and higher ICAM-1, CRP, IL-6, and TNFαR2 are also predictive of cardiovascular events, suggesting a potential explanation for a direct link between fatty liver and cardiovascular events." (PMID 28929125, 2017). "In addition, quantitative PCR revealed a decrease upon Cpd17 treatment in inflammatory markers F4/80, CCL2 and intracellular cell adhesion molecule (iCAM1), HSC‐specific marker α‐SMA and liver steatosis marker CCAAT‐enhancer‐binding proteins (C/EBP) (Fig EV4)." (PMID 35833384, 2022). "Our first major finding was that higher levels of proinflammatory biomarkers (ICAM-1, CRP, IL-6, and TNFαR2) and lower levels of the anti-inflammatory adiponectin were associated with fatty liver among HIV-uninfected men independent of VAT." (PMID 28929125, 2017). "It is notable that ICAM-1 and CRP were also associated with fatty liver independent of VAT among HIV-uninfected men." (PMID 28929125, 2017). "ICAM-1 and P-selectin levels are significantly increased in subjects with liver steatosis and elevated ALT in comparison with those without fatty liver." (PMID 38672744, 2024). "VSL#3 intervention failed to modulate the liver steatosis score in ApoE−/− mice, but completely reverted the progression of liver inflammation and fibrosis in ApoE−/− mice exposed to DSS (p<0.05; n = 8–12), and reduced the liver content of TNFα, RANTES, ICAM-1, and MIP-1α (p<0.05; n = 5)." (PMID 23029000, 2012).